CSF1R (colony stimulating factor 1 receptor)
Diseases named in the same sentence as CSF1R in open-access papers (continued):
Sharing a sentence is not in itself a finding about the gene and the disease.
tumor (continued). "Furthermore, a significant reduction of CSF1R+ cells distribution in the tumor and spleen of the conditional knockout mice compared to the wild type mice treated with vehicle and SB225002 was noted." (PMID 33544755, 2021). "The CSF1R mAb has to reach the tumor to deplete these protumor macrophages." (PMID 34976826, 2021). "CSF-1R and macrophages are the front line of defense to prevent tumor growth." (PMID 32760707, 2020). "Tumor-infiltrating macrophages can be targeted via CSF-1R inhibitors." (PMID 33488754, 2020). "However, subsequent studies found development of resistance to the CSF1R blockage through IGF1 secretion by TAMs resulting in resumed PI3K dependent tumor growth." (PMID 32555306, 2020). "CSF-1/CSF-1R blockade promotes antitumor T cell responses and reduces tumor growth in several preclinical models in combination with immunotherapy, despite showing minor effects on tumor growth as a monotherapy." (PMID 32793228, 2020). "Blocking the binding of macrophage colony-stimulating growth factor with receptors such as CSF-1R could lead to tumor rejection." (PMID 32359357, 2020). "Many studies on targeted therapy are based on a purposeful strategy of CSF1/CSF1R, that is, to focus on the recruitment of TAMs and the secretion of cytokines, tumor cells secrete CSF1 for the purpose of collecting TAMs by connecting CSF1 with CSF1R on macrophages." (PMID 32161718, 2020). "Preclinical evaluations demonstrate that combination of CSF1R inhibition after radiation therapy may more effectively decrease tumor volume." (PMID 33381449, 2020). "Finally, tumor cells produce Csf1 and IL-34 which recruit immunosuppressive Csf1r+ TAMs that produce IL-6, IL-10, and TGFβ, all factors that promote a cycle of immune suppression." (PMID 33584701, 2020). "In addition, some immune cell subsets with anti-tumor function, such as cytotoxic and gamma-delta T cells, were actively expressed in the CSF1R high-expressed group." (PMID 32850346, 2020). "Depletion of LAMs by a CSF‐1R inhibitor enhanced the anti‐tumour effects of VCR in mice with T‐ALL." (PMID 33037771, 2020). "The failure of CSF1R blockade to promote tumor rejection prompted us to investigate other mechanisms of immune suppression that may reflect additional effects of tumor cells on T cell function." (PMID 31940491, 2020). "Additionally, CSF1R expression was significantly elevated when demethylated, resulting in tumor metastasis promotion in melanoma." (PMID 32724427, 2020). "Thus, inhibition of CSF-1R signaling can significantly block the number of tumor-infiltrating MDSCs number and enhance anti-tumor T cells responses in tumor bearing mice." (PMID 33384962, 2020). "CSF1R expression in ANTs was also revealed to be significantly higher than that of tumor tissues." (PMID 32724427, 2020). "CSF-1/CSF-1R signaling has undergone relatively explicit investigation so far, the well-known fact that CSF-1 can attract, polarize, and sustain TAMs infiltrating in the tumor microenvironment, especially in PDAC with affluent stroma." (PMID 33505964, 2020). "Treatment with agonist anti-CD40 mAbs induced TAM immunostimulatory and tumor inhibitory effects in mouse tumor models both alone and in combination with anti-CSF1R mAb, by enhancing antigen-presentation and pro-inflammatory cytokine production and priming naive T lymphocytes." (PMID 32456204, 2020). "Moreover, targeting of TAMs with a selective CSF-1R inhibitor (AZD7507) in a genetic PDAC mouse model dramatically reduced tumor growth, enhanced T cell immune response and increased mouse survival in a difficult-to-treat model." (PMID 32509781, 2020). "CSF-1R regulates macrophage differentiation, polarization, and migration of macrophages and hence CSF-1R signaling has been targeted by small molecules and antibodies to deplete macrophages in the tumor microenvironment." (PMID 32326073, 2020).
tumor (continued). "Similarly, in MMTV-Neu transgenic mice, inhibiting the CSF1/CSF1R pathway by a CSF1 inhibitor named GW2580 led to a noticeable decrease of TAMs infiltration in tumor tissue." (PMID 32161718, 2020). "Methylation levels of CSF1R in ANTs may therefore be utilized to predict tumor progression in patients with HCC." (PMID 32724427, 2020). "The combination of either CD4 or CD68 with CSF1R predicted a more favorable prognosis (p < 0.01), suggesting that coordinated interaction between tumor antigen-specific CD4+ Th1 cells and CSF1R might participate in macrophage polarization toward CD68+ M1 TAM." (PMID 32850346, 2020). "CSF1‐R antagonism had little effect on inflammatory response in the circulation, liver, or tumor." (PMID 32039522, 2020). "This “re-education” shifts them toward an anti-tumorigenic phenotype and results in a decrease in the expression of tumor growth factors, a decrease in tumor size, and an increase in overall survival, suggesting CSF-1R signaling acts in an immunoregulatory capacity." (PMID 33027976, 2020). "CSF1 might negatively regulate inflammatory responses by activating PI3K230, and CSF1R is expressed on both tumor-suppressing and tumor-promoting myeloid cells." (PMID 32801364, 2020). "Since M-CSF also mediates the polarization of macrophages to the tumor-promoting type, the targeting of the M-CSF/CSF-1R axis, represents an attractive therapeutic approach and has shown efficacy in cancer metastasis models and in several murine models of cancer." (PMID 32656079, 2020). "Results from preclinical studies on CRC mouse models showed that the use of an anti-CSF1R antibody could delay tumor growth by decreasing levels of tumor-infiltrating MDSCs." (PMID 32090113, 2020). "Furthermore, immunofluorescence showed that CSF-1R were largely located in the margin of xenograft tumor and IFRA models." (PMID 32760707, 2020). "Inhibition of CSF‐1R was able to deplete TAMs and inhibit their tumour‐promoting function." (PMID 33037771, 2020). "Moreover, the colony-stimulating factor-1 receptor (CSF-1R) is a tyrosine kinase receptor that, when combined with the receptor, can induce the formation of MDSCs and trafficking to tumor sites." (PMID 32942545, 2020). "Tumours were reduced when tumour-bearing mice were treated with both the CSF1R inhibitor and a C–X–C Motif Chemokine Receptor 2 (CXCR2) antagonist (to prevent PMN-MDSC migration), and tumours were completely blocked when a PD-1 antibody was added to this combination." (PMID 31289350, 2019). "The presence of MDSC and their role in tumor protection in HL also calls for testing of combinations with novel modulators such as colony-stimulating factor 1 receptor (CSF1R) inhibitors, since MDSCs express CSF1R." (PMID 30841880, 2019). "Moreover, CSF1R inhibitor combined with the treatment abrogating the increased MDSC infiltration resulted in significant delay in tumor progression." (PMID 31438996, 2019). "However, abrogation of CSF1R signaling, by either small molecules or monoclonal antibodies, even though appealing, have so far demonstrated a limited anti-tumor effects." (PMID 31447834, 2019). "Thus, CSF1-R targeting leads to different consequences in the TIME, causing either depletion or macrophage reprogramming in a tumor-specific manner." (PMID 31611871, 2019). "The first approach includes the elimination of TAM and monocyte accrual to the tumor site through the inhibition of mainly CSF-1/CSF-1R (Colony Stimulating Factor 1/ Colony Stimulating Factor 1 Receptor) and CCL2/CCR2 (C-C Motif Chemokine Ligand 2/ C-C Motif Chemokine Receptor 2) signaling axes." (PMID 31060337, 2019).
tumor (continued). "In vivo contrast-agent free FeMRI was then used to quantify macrophage iron deposits of the MMTV-PyMT models in the BLZ945 trials, and correlate their detection with the CSF1R inhibitor’s primary immunotherapeutic effects on macrophage accumulation and tumor growth." (PMID 30696910, 2019). "Similarly, the inhibition of CSF-1 receptor (CSF-1R) is being use as strategy to inhibit tumor proliferation mediated by MDSCs." (PMID 30781344, 2019). "Studies have also shown that CSF-1R inhibition may sensitize tumor cells to more traditional cytotoxic therapy." (PMID 31439034, 2019). "There are several CSF-1R inhibitors currently in clinical trials in many tumor types." (PMID 31474975, 2019). "For instance, treatment with CSF1R antagonists in combination with checkpoint blockade-based immunotherapy in the mouse models of pancreatic, breast, cervical, and ovarian cancer results in delaying tumor progression." (PMID 31805946, 2019). "Preclinical studies using mouse models observed that CSF1R blockade dramatically reduced TAMs but accompanied by an accumulation of tumor-infiltrating bone marrow-derived suppressor cells (MDSCs), which may result in moderate efficacy for CSF-1R inhibitors." (PMID 31438996, 2019). "Although TAM numbers were significantly reduced with CSF1 blockade, they exhibited a more activated phenotype that may be due to increased inflammation within the tumor as was shown with a CSF1R inhibitor." (PMID 31552020, 2019). "CSF-1R signaling has specifically demonstrated a role in differentiation, maintenance, trafficking, functioning of the monocytic lineage, and serves as a prominent driver in resident tumor macrophages." (PMID 31428580, 2019). "Therefore, targeting CSF1/CSF1R is an attractive treatment for inhibition of TAMs to suppress tumor development." (PMID 31629410, 2019). "Similarly, the use of small molecule inhibitors or antisense RNA strategies to inhibit CSF-1R signaling, also inhibited tumor growth in both xenograft and genetically engineered mouse models." (PMID 31370273, 2019). "Furthermore, the inhibition of colony-stimulating factor 1 (CSF1)/CSF1 receptor (CSF1R) signaling can functionally block tumor-infiltrating MDSCs enhancing anti-tumor T cell responses and sensitizes IDO-expressing tumors to ICB in various tumor models." (PMID 30898166, 2019). "Treatment continued until control tumors reached or exceeded 1 cm3 measured by caliper to establish pre-treatment and endpoint imaging time points, and significant tumor growth inhibition was observed in both models with CSF1R inhibition by these endpoints (p < 0.001–p < 0.0001)." (PMID 30696910, 2019). "Thus, tumor cell secretion of CSF-1 is sensed by macrophages through CSF-1R and PI3K p110α, leading to induction of the NKG2D ligand RAE-1δ." (PMID 29757143, 2018). "In addition, we show that combinations of CSF1R inhibitors with tumor-directed therapies in CLL (ibrutinib or idelalisib) exhibit strong synergy across numerous CLL patient specimens." (PMID 29872489, 2018). "Moreover, these tumors are also highly enriched in factors that recruit or support suppressive monocytic MDSC or tumor associated macrophage populations (CCR2, CSF1R, and GM-CSF/CSF2)." (PMID 30388137, 2018). "Secretion of CSF-1 by GBM impacts tumor progression through CSF1R signaling." (PMID 30854331, 2018). "In addition to identifying the optimal tumor types for CSF1R inhibition, proper dosing schedules will also need to be determined." (PMID 29946544, 2018). "Furthermore, CSF-1/CSF-1R also showed a higher correlation with tumor infiltrating lymphocytes (TILs) than IL-34, PTPRZ1, and syndecan-1." (PMID 29796177, 2018). "CSF-1, CSF-1R, and IL-34 were weakly negatively associated with tumor purity, while the lack of association between immune cell infiltration and gene expression of PTPRZ1 and syndecan-1 was also reflected by tumor purity values." (PMID 29796177, 2018).
tumor (continued). "As it has been shown that steady-state CSF-1 signaling is necessary for monocyte and macrophage survival in vivo, we injected tumor-bearing mice with CSF-1R antibody and monitored tumor-infiltrating macrophage numbers and RAE-1δ expression at various time points." (PMID 29757143, 2018). "The conversion of exhausted PD-1+ T-cells to CD137+ activated effector T-cells may contribute to the anti-tumor effects of the anti-CSF-1R/anti-PD-1/GVAX combination therapy." (PMID 30424804, 2018). "CSF1R-expressing TAMs induce a tumor-promoting microenvironment by regulating immunity." (PMID 30065206, 2018). "For instance, TAMs could be re-educated into an anti-tumor phenotype by CSF-1R inhibition or by pattern recognition receptor (PRR) ligands, which inhibited tumor growth in a mouse model of glioblastoma multiforme and lung cancer, respectively." (PMID 30355585, 2018). "In addition, inhibition of either CCR2 or CSF-1R has been shown to decrease the chemotherapy-resistance of pancreatic tumors and to increase the T-cell mediated anti-tumor immune response in mice." (PMID 30349530, 2018). "Established tumors can escape immune responses by secreting the cytokine colony stimulating factor 1 (CSF-1), stimulating the proliferation and recruitment of immunosuppressive myeloid cells to the tumor microenvironment by binding to colony stimulating factor-1 receptor (CSF-1R)." (PMID 30400835, 2018). "However, CSF1R blockade in combination with either an antibody against PD-1 or CTLA-4, except for gemcitabine, led to improved tumor regression, suggesting that CSF1R blockade induced reduction of TAMs and enabled response to ICB." (PMID 29482595, 2018). "Of all interventions studied, we found that CSF1R inhibition has the most profound effect causing tumor regression and T cell activation, independent of PD1 inhibition." (PMID 29719257, 2018). "Finally, other combinations of ICKB and targeting the tumor microenvironment include antagonist mAbs for M-CSF/CSF1 (NCT02807844) or its receptor MCSFR/CSF1R (NCT02452424 and NCT02880371)." (PMID 28970830, 2017). "Indeed, pharmacological inhibition, neutralising monoclonal antibodies, or genetic mutation of chemoattractants such as CCL2, VEGFR2, CSF-1R depleted TAM infiltration and reduced tumour growth." (PMID 29065107, 2017). "Genetic or therapeutic targeting of the CSF‐1/CSF‐1 receptor (CSF‐1R) pathway in different tumor models leads to varying degrees of macrophage depletion; this has been found to have direct anti‐tumor activity or to potentiate the response to chemotherapy, often with anti‐angiogenic effects." (PMID 29127101, 2017). "The CSF1/CSF1R pathway is critical in recruiting TAMs and promoting tumor growth." (PMID 28348554, 2017). "Targeting multiple kinases to simultaneously block VEGFR-, FGFR-, and CSF1R-mediated pathways may be a more effective method of preventing tumor angiogenesis and tumor immune evasion, and therefore represents an attractive anti-cancer therapy approach." (PMID 28159938, 2017). "Likewise, 1-week treatment of tumor-injected C57BL/6 mice with a specific CSF1R antagonist BLZ945 reduced the number of MAMs in the lung without affecting the number of MAMPCs and C-MOs." (PMID 29387063, 2017). "Moreover, CSF1R blockade exemplifies the status quo, which seeks to target TAMs indiscriminately even though TAMs can play both tumor-supportive and anti-tumor roles." (PMID 29262845, 2017). "Overall, CSF1-R inhibitors deplete TAMs and abolish tumor growth, angiogenesis, and metastasis." (PMID 28769933, 2017). "Furthermore, anti-CSF-1/CSF-1R therapies have produced encouraging therapeutic responses in pre-clinical tumour models, particularly in combination with chemotherapy or radiotherapy, or when used to reprogram tumor-promoting TAMs into anti-tumoral TAMs." (PMID 28629162, 2017). "Previous studies revealed the importance of CSF-1/CSF-1R expression in various tumor types." (PMID 29228668, 2017).
tumor (continued). "It is here speculated that the low expression of CSF-1R in inflammatory and immune cells likely attenuated their migratory ability and ability to infiltrate into tumor, and thus facilitate tumor metastasis in Nur77-/- mice." (PMID 28170411, 2017). "Taken together, this study identified a distinct population of MAM precursor in the metastatic sites that accumulate during the metastatic tumor growth by CSF1R independent mechanism, and suppress CD8+ T cell cytotoxicity by a ROS-mediated but checkpoint receptor-independent mechanism." (PMID 29387063, 2017). "Hence, the combination of tumor-targeted or anti-angiogenic therapies and CSF1R inhibitors resulted in improved anti-tumoral activity." (PMID 28716061, 2017). "This may be due to the effect of CSF-1R inhibition on anti-tumoral macrophage populations as functionally distinct TAM populations are found within tumours." (PMID 28629162, 2017). "A recent study reported that depletion of TAMs from the tumor tissues by an anti-CSF-1R antibody may hold promise in the treatment of some solid tumors." (PMID 26799669, 2016). "In glioblastoma mouse models, striking inhibition of CSF-1R could result in a dramatic reduction in tumor volume and long-term survival of the mice." (PMID 27191744, 2016). "Moreover, the blockade of CSF1R signaling was found not only to block the MDSC trafficking to tumor lesions but also improve the efficacy of radiotherapy in the prostate cancer model." (PMID 27827871, 2016). "The Sphere Forming Assay is considered by some as a surrogate of tumor initiation in vivo and thus our previous observations may unravel a potential usefulness of the CSF-1R TKI in vivo." (PMID 27486763, 2016). "Additionally, tumor tissue from both genotypes was populated by prominent numbers of Csf1R expressing cells." (PMID 26755653, 2016). "Clearly, it remains to be addressed how the double effects of the TKI at inhibiting CSF-1R expressed by both tumor-infiltrating immune components and by the tumor cells is balanced in more clinically relevant settings and how this can be exploited, therapeutically." (PMID 27486763, 2016). "Results from the current paper showing evidence of close physical interactions between CSF1R+ TAMs and tumour HRS cells and phosphorylation, and therefore activation, of the CSF1R pathway in cHL tumour tissues provides further evidence of an important role for this pathway in cHL." (PMID 26066800, 2015). "Here, we show that CSF1R inhibition can have a detrimental effect on tumor therapy, not only by depleting macrophage effector cells but also by impairing the activation of tumor-specific T cells during immunotherapy." (PMID 26635798, 2015). "Blocking monocyte entry into the lymph node and tumor through neutralization of the chemokine CCL2 or inhibition of colony-stimulating factor-1 receptor signaling prevented the generation of moDCs, the infiltration of tumor-specific T cells into the tumor, and antitumor responses." (PMID 26635798, 2015). "Moreover, use of an anti-CSF1R antibody depletes TAMs in animal models and also in human tumours, also suggesting therapeutic potential in cancer." (PMID 26066800, 2015). "In view of the recent reports describing the expression of CSF1R protein in cell lines and CSF1R mRNA in tumour cells of cHL cases, double immunoenzymatic and immunofluorescence labelling studies were also performed in cHL tumours, showing that CD30+ HRS cells lack detectable CSF1R." (PMID 26066800, 2015). "Moreover, in a mouse model of pancreatic ductal adenocarcinoma, blockade of CSF-1/CSF-1R signaling results in macrophage reprograming to support anti-tumor immune function and modestly delays tumor growth." (PMID 26500653, 2015). "Additionally, CSF-1R has been shown to polarize macrophages towards an immunosuppressive and tumor-promoting direction." (PMID 25110953, 2014).